AFP (alpha fetoprotein)
Diseases named in the same sentence as AFP in open-access papers (continued):
Sharing a sentence is not in itself a finding about the gene and the disease.
hepatocellular carcinoma (continued). "AFP is a tumor marker used for screening for hepatocellular carcinoma (HCC) and was the reason that it was checked in this patient with chronic hepatitis B. AFP-producing urothelial tumors are extremely rare." (PMID 30208947, 2018). "The GAuNP aggregates that were formed were then used as a supramolecular glycoprobe for the rapid detection of α-fetoprotein (AFP)-L3, a protein which binds strongly to LcA and is a serological biomarker for hepatocellular carcinoma (HCC)." (PMID 29379576, 2018). "The present study investigated the prognostic significance of PLCE1 gene polymorphisms and expression combined with serum α-fetoprotein (AFP) level in hepatitis B virus (HBV)-related hepatocellular carcinoma (HCC)." (PMID 28418898, 2017). "Serum alpha-fetoprotein (AFP) levels elevated in benign liver diseases (BLD) represent a challenge in hepatocellular carcinoma (HCC) diagnosis." (PMID 29228649, 2017). "Moreover, baseline anti-HBc levels, combining vascular invasion and alpha-fetoprotein (AFP) levels might be a novel biomarker for predicting the survival of hepatocellular carcinoma patients after transarterial chemoembolization." (PMID 29074971, 2017). "As a promising biomarker, the expression of LARP1 is closely related to poor prognosis of early-stage and alpha-fetoprotein-normal hepatocellular carcinoma (HCC) patients." (PMID 27614686, 2016). "Serum alpha-fetoprotein (AFP) is recognized as a hepatocellular carcinoma (HCC)-specific marker, and older HCC guidelines included serum AFP measurement, combined with imaging studies, in the protocol for surveillance and diagnosis of HCC." (PMID 27304617, 2016). "Besides, whether the AFP gene is post-transcriptionally regulated in hepatoma cells remains unknown." (PMID 27835879, 2016). "In addition to the secretion of AFP, 90% of hepatocellular carcinoma cells express telomerase." (PMID 25822740, 2015). "Alpha-fetoprotein (AFP) has long been used as a tumor marker for hepatocellular carcinoma (HCC) and embryonic cell tumors." (PMID 25886790, 2015). "Changes in intra-tumor blood flow on CE-CT, AFP levels, and remnant liver function after 2 weeks of sorafenib therapy may be useful for predicting the outcomes and anti-tumor response to sorafenib in patients with advanced hepatocellular carcinoma." (PMID 26421430, 2015). "An increase in total AFP concentration in the serum was originally used as an indicator for hepatocellular carcinoma (HCC); however, measuring the total AFP concentration cannot always discriminate between small HCCs and chronic liver disease." (PMID 28248271, 2015). "The aim of the present study was to construct a gene-modified hepatocellular carcinoma (HCC)-specific analgesic-antitumor peptide (AGAP) expression vector regulated by the α-fetoprotein (AFP) promoter and enhancer, in order to evaluate its effect." (PMID 25667643, 2015). "Because elevation of serum AFP, a common marker for hepatocellular carcinoma (HCC), also occurs in non-HCC conditions such as pregnancy, AFP-L3, consisting of core-fucosylated glycoforms of AFP, provides better specificity for HCC." (PMID 24872809, 2014). "Hepatocellular carcinoma (HCC) can be diagnosed by noninvasive approaches with serum α-fetoprotein (AFP) levels >200 ng/ml and/or a radiological imaging study of tumor mass >2 cm in patients with chronic liver disease." (PMID 25170868, 2014). "HAC is defined by the reproduction of a pattern similar to that of a hepatocellular carcinoma, with a combination of histopathological findings of solid nests and trabecular structures of polygonal atypical cells with wide granular cytoplasm and an immunochemical expression of AFP." (PMID 23302376, 2013). "The clinical value of Serum alpha-fetoprotein (AFP) to detect early hepatocellular carcinoma (HCC) has been questioned due to its low sensitivity and specificity found in recent years." (PMID 24317431, 2013).
hepatocellular carcinoma (continued). "We studied the relationships among Cx43, CD105, and VEGF in specimens of hepatitis B virus (HBV)-related hepatocellular carcinoma (HCC) with different serum AFP levels with respect to recurrence and metastasis." (PMID 23800357, 2013). "Alpha-fetoprotein (AFP) has been considered for a long time the ideal serological marker for detecting hepatocellular carcinoma (HCC)." (PMID 22792474, 2012). "As we know, AFP is a common critical index in HCC progression, and BCLC and TNM stages reflect the progression stage of hepatocellular carcinoma." (PMID 23282077, 2012). "The first serologic assay for detection and clinical followup of patients with hepatocellular carcinoma was alpha-fetoprotein (AFP) which has been the standard tumor biomarker for HCC for many years." (PMID 22655201, 2012). "In hepatocellular carcinoma (HCC) patients with high levels of AFP, antigen presenting cells (APCs) are dysfunctional." (PMID 21235824, 2011). "Tumor cells in hepatoid foci resemble the morphology of hepatocellular carcinoma (HCC), and immunohistochemically can be positive for AFP, alpha-1 antitrypsin (AAT), alpha-1 antichymotrypsin (ACT) and albumin (ALB)." (PMID 20062620, 2009). "In the adult liver, AFP is expressed in only very small amounts; nonetheless, AFP expression can resume in certain pathophysiological situations, such as liver regeneration (e.g., after surgical resection) and liver carcinogenesis (e.g., hepatocellular carcinoma)." (PMID 16822301, 2006). "The expression of α-fetoprotein (AFP), a biomarker for hepatocellular carcinogenesis, was increased in transplacental arsenic-induced hepatocellular carcinoma (HCC) and tumor-surrounding tissues." (PMID 15345372, 2004). "The purpose of this study was to compare alpha-L-fucosidase and alpha-fetoprotein as serum markers of hepatocellular carcinoma in 72 southern African blacks with this tumour and 64 matched patients with benign hepatic diseases which might be mistaken clinically for hepatocellular carcinoma." (PMID 2467686, 1989). "Hepatocellular carcinoma (HCC) is typically identified by markers such as arginase-1, GPC3, HepPar-1, and AFP, while cholangiocellular carcinoma (CCC) is positive for CK19 and CK8." (PMID 41515615, 2026). "Hepatocellular carcinoma (HCC) typically develops in a cirrhotic background, where elevated serum α-fetoprotein (AFP), a commonly used HCC biomarker, performs inconsistently." (PMID 42304605, 2026). "Despite the development of numerous prognostic models for hepatocellular carcinoma (HCC) recurrence and mortality after liver transplantation, tumor biomarkers such as alpha-fetoprotein (AFP) and protein induced by vitamin K absence-II (PIVKA-II) remain widely used in clinical practice." (PMID 40656560, 2025). "In a hepatocellular carcinoma (HCC) mouse model, the isolated EVs carrying α-fetoprotein (AFP), a liver protein highly expressed in HCC patients, demonstrated a strong antigen-specific response by shifting the TME from immuno-inhibitory to immunostimulatory post-administration." (PMID 40872479, 2025). "MRM has been applied to quantify a panel of biomarkers, such as GP73, AFP, and DKK1, in the plasma of hepatocellular carcinoma patients, demonstrating its utility in multiplex profiling." (PMID 41008874, 2025). "Since infancy, she has been regularly monitored for chronic cholestasis, which progressed to infiltrative hepatocellular carcinoma (HCC) diagnosed in 2015 at age 20, on a cirrhotic liver secondary to her genetic condition, her initial alpha-fetoprotein (AFP) was elevated at 282 ng/mL." (PMID 40492163, 2025). "Alpha-fetoprotein (AFP) is used in clinical screening and can help in the evaluation of hepatocellular carcinoma (HCC)." (PMID 40699758, 2025). "After logistic multifactorial analysis, intact envelope, tumor > 5 cm, AFP, CAR, CD147, and IL-6 were identified as independent influencing factors for invasive metastasis of primary hepatocellular carcinoma (all p < 0.05)." (PMID 40919145, 2025).
hepatocellular carcinoma (continued). "In non-viral hepatocellular carcinoma (HCC), plasma EV miR-19-3p showed strong diagnostic accuracy, showing excellent detection capability for early-stage and AFP-negative HCC." (PMID 40643544, 2025). "Histologically and immunophenotypically, it closely resembles hepatocellular carcinoma (HCC), often presenting with markedly elevated serum alpha-fetoprotein (AFP) levels." (PMID 40919162, 2025). "Here, we analyzed nine tumor markers (CA19‐9, AFP, PSA, CEA, CA125, CYFRA, CA15‐3, SCC antigen, and NCC‐ST439) in 119 patients with pancreatic cancer and 49 with hepatocellular carcinoma, alongside 590 healthy controls." (PMID 40589150, 2025). "In this case, the positive expression of HepPar-1, AFP, glypican-3 and CK7/CK19 is in agreement with the features of hepatocellular carcinoma." (PMID 39931054, 2025). "It was also able to distinguish betweenpatients with hepatocellular carcinoma, patients with cirrhosis, andhealthy donors with remarkable accuracy, surpassing traditional clinicalindicators like the AST/ALT ratio, CEA, and AFP." (PMID 40720603, 2025). "Alpha-fetoprotein (AFP) is a universally recognized tumor marker in hepatocellular carcinoma (HCC)." (PMID 41262237, 2025). "Despite alpha-fetoprotein (AFP) serving as the gold standard for liver cancer diagnosis, 80% of small hepatocellular carcinomas and early-stage hepatocellular carcinomas remain undetected by AFP testing." (PMID 41013140, 2025). "Alpha-fetoprotein (AFP) is typically found in the serum and serves as an early biomarker for hepatocellular carcinoma, and carcinoembryonic antigen (CEA) is overexpressed in cancers such as gastrointestinal cancers, breast cancer, and pancreatic cancer." (PMID 39791822, 2025). "Alpha-fetoprotein (AFP), a serum protein synthesized by the yolk sac and liver during embryonic development, has been shown to be closely associated with hepatocellular carcinoma (HCC)." (PMID 40277545, 2025). "Understanding the significance of these biomarkers and their relationship with AFP could potentially improve the early detection of hepatocellular carcinoma (HCC) progression in HT-1 patients." (PMID 40332516, 2025). "For the completion of this narrative review, a literature search was performed via the PubMed, Scopus and Science Direct databases using the following keywords: HCC, hepatocellular carcinoma, MDK, midkine, NEGF-2, MK, and AFP." (PMID 38247828, 2024). "In hepatocellular carcinoma (HCC), its expression is significantly elevated and positively correlates with tumor size, serum AFP levels, organ invasion, and poor survival outcomes." (PMID 39199615, 2024). "AFP is a biomarker that has become widely used in the management of hepatocellular carcinoma (HCC)." (PMID 39064538, 2024). "Hepatocellular carcinoma (HCC) is a highly lethal malignant tumor, and the current non‐invasive diagnosis method based on serum markers, such as α‐fetoprotein (AFP), and des‐γ‐carboxy‐prothrombin (DCP), has limited efficacy in detecting it." (PMID 38327127, 2024). "The patient's alpha-fetoprotein (AFP) test result was within the normal range, ruling out hepatocellular carcinoma." (PMID 39610672, 2024). "Hepatocellular carcinoma (HCC) has a poor prognosis, and alpha-fetoprotein (AFP) is widely used to evaluate HCC." (PMID 38438972, 2024). "One such secretory protein, the alpha-fetoprotein (AFP), has been employed in the diagnosis of various cancers, including hepatocellular carcinoma, yolk sac tumor, tumors of gonadal origin, and specific types of gastric cancers (GC)." (PMID 39902132, 2024). "Serial analysis of gene expression showed that MYDGF was highly expressed in hepatocellular carcinoma (HCC), significantly and positively correlated with AFP, and promoted the proliferation of HCC cell lines through the AKT/MAPK pathway." (PMID 39030488, 2024).
hepatocellular carcinoma (continued). "Alpha-fetoprotein (AFP) is a specific marker for YST, but it lacks sensitivity since elevated levels can also be observed in other conditions, such as hepatocellular carcinoma." (PMID 39590141, 2024). "Alpha-fetoprotein (AFP) elevation is a well-known biomarker in various diseases, particularly in the diagnosis of hepatocellular carcinoma (HCC)." (PMID 39135041, 2024). "Compared to AFP, CLU proves to be a superior biomarker for the diagnosis of hepatocellular carcinoma." (PMID 37685987, 2023). "The same approach was implemented to detect, in addition to AFP, the Lens culinaris agglutinin (LCA)-reactive fraction of AFP (AFP-L3), another marker of hepatocellular carcinoma, in a single run." (PMID 37241360, 2023). "Alpha-fetoprotein (AFP) and des-gamma-carboxyprothrombin (DCP) are widely used as tumor markers to diagnose hepatocellular carcinoma (HCC)." (PMID 36672339, 2023). "Guidelines vary on alpha-fetoprotein (AFP) testing for hepatocellular carcinoma (HCC) screening." (PMID 38201578, 2023). "Although the RETREAT score improves hepatocellular carcinoma (HCC) recurrence prediction post liver transplantation (LT), there is a necessity for more discriminating models in low alpha-fetoprotein (AFP) populations." (PMID 38201435, 2023). "Alpha-fetoprotein (AFP) is among the earlier cancer biomarkers examined in humans and is a key biomarker for the early detection of hepatocellular carcinoma." (PMID 37110837, 2023). "Age, TNM stage, alpha-fetoprotein status before treatment, surgery, radiotherapy and chemotherapy are independent prognostic factors for patients with stage III hepatocellular carcinoma." (PMID 37312022, 2023). "In hepatocellular carcinoma (HCC), hypermetabolic subclusters displayed low α-fetoprotein (AFP) expression, and good prognosis while subclusters with intermediate metabolic activity displayed high AFP expression level and bad prognosis." (PMID 36829161, 2023). "Hepatoid adenocarcinoma (HAC) is a highly malignant and rare extrahepatic tumor histologically similar to hepatocellular carcinoma (HCC) and characterized by high serum α-fetoprotein (AFP)." (PMID 37161409, 2023). "Early detection of hepatocellular carcinoma (HCC) traditionally involves surveillance through techniques such as ultrasonography (US) and serological measurements of alpha-fetoprotein (AFP)." (PMID 37892997, 2023). "Alpha-fetoprotein (AFP) is a well-identified biomarker in hepatocellular carcinoma (HCC)." (PMID 36686731, 2022). "*Abbreviations: AFP – alpha-fetoprotein; HCC – hepatocellular carcinoma; MELD – Model for End-Stage Liver Disease." (PMID 35505652, 2022). "Alpha-fetoprotein (AFP) is an oncofetal protein that is elevated in a subset of hepatocellular carcinoma (HCC) with poor prognosis, but the molecular target activated in AFP-positive HCC remains elusive." (PMID 35955438, 2022). "The expression of TFR1 protein in tumor tissues of hepatocellular carcinoma (HCC) patients was found significantly higher than that in adjacent tissues, and the expression of TFR1 in HCC is related to the level of AFP." (PMID 36082181, 2022). "Alpha-fetoprotein (AFP), a commonly used hepatocellular carcinoma biomarker, is the most upregulated protein identified in COVID-19 positive patient nasopharyngeal samples (p < 0.0001, log2FC = 2.26)." (PMID 36094909, 2022). "As a proof of the principle, alpha fetoprotein (AFP), which has been a routinely used biomarker for the early screening of hepatocellular carcinoma (HCC), was used as the test glycoprotein biomarker in this study." (PMID 35656127, 2022). "Furthermore, in an in vivo model of hepatocellular carcinoma (HCC), fucoidan significantly improved survival, inhibited cellular proliferation, and decreased serum AFP expression levels in HCC rats." (PMID 36532760, 2022).
hepatocellular carcinoma (continued). "Here, we report a nanoparticle-on-mirror (NPOM) plasmonic sensor excited by surface plasmon polaritons (SPPs) to realize quantitative SERS detection of alpha fetoprotein (AFP), one biomarker for hepatocellular cancer." (PMID 39634743, 2022). "Alpha-fetoprotein (AFP) is a specific tumor marker and commonly used in the diagnosis of hepatocellular carcinoma and yolk sac tumor." (PMID 35847953, 2022). "An elevated level of AFP may also indicate liver injury and the early stages of chemical hepatocarcinogenesis, so it can be an indicator of hepatocellular carcinoma (HCC)." (PMID 36684957, 2022). "Hepatoid adenocarcinoma (HAC) is an extremely rare extrahepatic carcinoma, which is pathologically featured by hepatocellular carcinoma (HCC) and marked by producing alpha-fetoprotein (AFP)." (PMID 35515120, 2022). "Another liquid biopsy cancer biomarker that was once regarded to be the one that might bring screening and diagnosis in case of hepatocellular carcinoma (HCC) to another level was Alpha-fetoprotein (AFP)." (PMID 35966579, 2022). "Report mentioned that elevated serum AFP and CEA were found in advanced hepatocellular carcinoma with extrahepatic metastasis." (PMID 35461226, 2022). "For patients with advanced hepatocellular carcinoma, this model has better recognition ability than ALBI, Child-Pugh and AFP." (PMID 33835138, 2021). "Specific glycoproteins incorporating aberrant glycans have been uncovered with significantly higher specificity for cancers than the proteins themselves, such as glycosylated alpha-fetoprotein (AFP), which serves as a more reliable marker for hepatocellular carcinoma (HCC) than AFP protein." (PMID 34199928, 2021). "The repression of AFP by HBP1 attenuated AFP effect on PTEN, MMP9 and caspase-3, thus inhibited proliferation and migration, and induced apoptosis in hepatoma cells." (PMID 33794968, 2021). "Patients with hepatocellular carcinoma (HCC) exceeding the Milan criteria and an immediate pretransplant AFP > 400 ng/mL had unfavorable survival outcomes following living-donor liver transplantation." (PMID 34065172, 2021). "Regarding tumor growth regulation by AFP, LOX-1 has been reported to be expressed mainly on DCs, hepatoma cells, breast and ovarian adenocarcinomas, lymphomas, and prostate tumors to promote tumor growth." (PMID 33718192, 2021). "Serum AFP is a widely accepted serum marker for the detection of hepatocellular carcinoma (HCC)." (PMID 34746648, 2021). "However, AFP expression is up-regulated in 70–80% of patients with hepatocellular carcinoma (HCC), and is a known tumor marker in the clinical diagnosis of HCC." (PMID 33765973, 2021). "In this study, we found a transcriptional regulatory mechanism to regulate the progression of hepatoma between HBP1 and AFP." (PMID 33794968, 2021). "Another member, ITIH4, has been demonstrated as a potential diagnostic marker in hepatocellular carcinoma (HCC) that was even superior to AFP; it exhibited a strikingly lower concentration in HCC than normal controls and its expression level was declining during the progression of HCC." (PMID 33744857, 2021). "An abnormal alpha-fetoprotein (AFP) test is often associated with hepatocellular carcinoma (HCC) development, although as many as 40% of HCC diagnoses are made in the absence of an abnormal AFP test." (PMID 34638251, 2021). "In the present study, we found that HBP1 expression was also downregulated in hepatoma tissues, and overexpression of HBP1 in hepatoma cells transcriptionally inhibited AFP expression and decreased cell proliferation and migration." (PMID 33794968, 2021). "The Hepatocellular Carcinoma Early Detection Screening (HES) algorithm, which includes age, AFP, rate of AFP change, ALT, and platelet count, was validated in a phase II study in HCV-related HCC." (PMID 34754704, 2021).